PPP4R4 (protein phosphatase 4 regulatory subunit 4)
Description:
Putative regulatory subunit of serine/threonine-protein phosphatase 4.
Synonyms: KIAA1622; PP4R4; CFAP14
Tractability: PROTAC: its protein half-life has been measured.
Gene: Protein-coding gene on chromosome 14 (94,146,128 to 94,279,734, forward strand). Ensembl gene ENSG00000119698.
Subcellular location: Cytoplasm
Subcellular location (Human Protein Atlas): Cytosol; Basal body; Primary cilium
Gene Ontology:
Molecular function: protein binding; protein phosphatase inhibitor activity; protein serine/threonine phosphatase inhibitor activity; protein phosphatase regulator activity
Cellular component: cytoplasm; cytosol; protein serine/threonine phosphatase complex
Genetic constraint (gnomAD): Loss-of-function variants: 41 observed, 74.41 expected, observed/expected ratio (o/e) 0.55, 90% interval 0.43 to 0.71. The upper end of that interval is the gene's LOEUF score, 0.71, which puts it in group 2 of 6, group 1 being the genes least tolerant of losing a copy. Missense variants: 651 observed, 795.67 expected, observed/expected ratio (o/e) 0.82, 90% interval 0.77 to 0.87. Synonymous variants: 266 observed, 281.63 expected, observed/expected ratio (o/e) 0.94, 90% interval 0.85 to 1.04.
Homologues: Orthologues: chimpanzee PPP4R4 (99% identical), macaque PPP4R4 (99% identical), dog PPP4R4 (97% identical), pig PPP4R4 (96% identical), mouse Ppp4r4 (91% identical), rat Ppp4r4 (90% identical), rabbit PPP4R4 (90% identical), guinea pig PPP4R4 (89% identical), tropical clawed frog ppp4r4 (75% identical), zebrafish ppp4r4 (59% identical), Caenorhabditis elegans F46C5.6 (24% identical).
Diseases named in the same sentence as PPP4R4 in open-access papers:
PPP4R4 is named in the same sentence as 2 diseases in open-access papers, as found by Europe PMC text mining. Sharing a sentence is not in itself a finding about the gene and the disease.
PPP4R4 shares sentences with these, for which no sentence is quoted: Insulin resistance (1 paper); tumor (1).